CDK1 (cyclin dependent kinase 1)
Diseases named in the same sentence as CDK1 in open-access papers (continued):
Sharing a sentence is not in itself a finding about the gene and the disease.
hepatocellular carcinoma (continued). "Increased CDK1 expression has been observed in tumor cells, including pancreatic ductal adenocarcinoma, esophageal squamous cell carcinoma, and hepatocellular carcinoma." (PMID 35681641, 2022). "Metformin induces mir-378 to down-regulate CDK1, resulting in inhibition of proliferation of hepatocellular carcinoma cells." (PMID 36699068, 2022). "Blocking CDK1/PDK1/β-Catenin signaling would decrease stemness of cancer stem cells of hepatocellular carcinoma cells, and reverse sorafenib chemoresistance." (PMID 35078445, 2022). "Overexpression of CDK1 has been observed in different type cancers, including hepatocellular carcinoma, where it is correlated with poor OS." (PMID 36557005, 2022). "Another study showed that CDK1 inhibition enhanced the ability of the protein kinase inhibitor sorafenib to specifically kill stem cells of hepatocellular carcinoma." (PMID 34503199, 2021). "In hepatocellular carcinoma, miR-582-5p exerts growth-suppressive effects through negative regulation of CDK1 and AKT3." (PMID 34978519, 2021). "This was further confirmed by another study, which showed that the silencing of CDK1 reduced tumour growth of hepatocellular carcinoma CSCs by inhibiting their clonogenic potential and self-renewal ability." (PMID 34503199, 2021). "For instance, miR-1271-5p can repress cell viability and promote radiosensitivity through targeting CDK1 in hepatocellular carcinoma." (PMID 32948241, 2020). "The miRNA miR-582-5p is known to suppress the proliferation of a variety of tumors, including hepatocellular carcinoma, colon cancer, and bladder cancer, and this suppression is thought to be related to the target genes CDK1, AKT3, Rab27a, and FOXC1." (PMID 31146370, 2019). "We identified six mRNAs (DPYSL4, HOMER1, ABCB6, CENPA, CDK1, STMN1) significantly associated with overall survival in the Cox proportional regression model for hepatocellular carcinoma." (PMID 31790363, 2019). "In conclusion, costunolide specifically arrests cell cycle at mitosis accompanied by modulation of Chk2/Cdc25c/Cdk1/cyclin B1 signaling and enhancement of radioresponse in human hepatoma HA22T/VGH cells." (PMID 21624128, 2011). "In addition, CDK1 regulates HBV replication and can interact with HBV-encoded circRNA to regulate HBV-mediated hepatocellular carcinoma progression." (PMID 40408617, 2025). "Therefore, this study employed an integrated computational biology and machine learning approach to elucidate berberine’s mechanisms, identifying AURKA and CDK1 as its principal therapeutic targets against hepatocellular carcinoma." (PMID 41226349, 2025). "Importantly, the central role of AURKA and CDK1 in hepatocellular carcinoma is corroborated by independent clinical bioinformatics analyses which also identified these kinases as prognostic biomarkers in HBV-related HCC." (PMID 41226349, 2025). "During the multi-stage process of liver fibrosis to hepatocellular carcinoma transformation, the expression and function of CDK1 may change dynamically, and it is difficult for static histological data to reflect such temporal regulation." (PMID 40332418, 2025). "Future studies should further develop highly efficient and low-toxicity CDK1 inhibitors and strengthen the interface between preclinical studies and clinical trials to promote the widespread application of CDK1 inhibitors in the treatment of liver fibrosis and hepatocellular carcinoma." (PMID 40332418, 2025). "By comparing the data on hepatocellular carcinoma obtained from public databases, we found that the expression of CDK1 contributed to the effect of multiple immunosuppressants, while methylated CDK1 showed the opposite trend, namely, the effect of immunosuppressants." (PMID 40332418, 2025). "CDK1 inhibitor RO3306 could improve the efficacy of sorafenib treatment by targeting cancer stem cells in a preclinical model of hepatocellular carcinoma." (PMID 38605349, 2024).
hepatocellular carcinoma (continued). "In addition, studies have confirmed the inhibitory effect of SGLT2 inhibitors such as Canagliflozin on CDK1 and the subsequent cell cycle arrest at the G2/M in hepatocellular carcinoma." (PMID 38003585, 2023). "Furthermore, down-regulated expression of CDK1 not only inhibits proliferation and migration of hepatocellular carcinoma cells, but also induces cycle arrest and specific apoptosis of hepatocellular carcinoma cells." (PMID 38144520, 2023). "CDK1 has been reported to be upregulated in various cancers including hepatocellular carcinoma." (PMID 37377594, 2023). "As the previous study identified, CDK1 was overexpressed in hepatocellular carcinoma and was related to the development of tumor through the CDK1/PDK1/β-Catenin pathway, which could predict worse survival outcomes." (PMID 34187556, 2021). "In liver fibrosis, CDK1 may promote fibrosis through the activation of hepatic stellate cells (HSCs), whereas in hepatocellular carcinoma, it may drive tumor cell proliferation, but existing analyses often ignore cell-type specificity (e.g., without integrating single-cell sequencing data)." (PMID 40332418, 2025). "Therefore, we speculate that the inhibition of CDK1 expression is useful in treating hepatocellular carcinoma." (PMID 40332418, 2025). "A role for cyclinA2 and CDK1 in cell migration has been described in a range of cell types, including breast and hepatocellular cancer cells and Schwann cells in addition to the cell types used in this study, demonstrating a conserved role for cyclinA2–CDK1 complexes in motility." (PMID 40518827, 2025). "According to the different expression levels of the CDK1 gene in human HCC cells, hepatocellular carcinoma cases were divided into a high CDK1 expression group and a low CDK1 expression group." (PMID 40332418, 2025). "Cyclin-dependent kinase 1 (CDK1) has emerged as a critical regulator of cell cycle progression, yet its role in liver fibrosis-associated hepatocellular carcinoma (LF-HCC) remains underexplored." (PMID 40332418, 2025). "So, we speculated that CDK1 inhibitors can reduce the expression of the CDK1 gene in Tprolif cells, promote the proliferation of Tprolif cells, and strengthen the immunosuppressive effect of immune cells on hepatocellular carcinoma." (PMID 40332418, 2025). "Thus, CENPF-E2F1/CDK1 pathway mediating abnormal cell division in cell cycle might be a indispensable process in hepatocellular carcinoma." (PMID 33854594, 2021). "Xylocydine is a novel cyclin-dependent kinase (cdk) inhibitor that induces apoptosis in hepatocellular carcinoma (HCC) cells by inhibiting Cdk1, Cdk2, Cdk7, and Cdk9 activities." (PMID 23344045, 2013). "In hepatocellular carcinoma, CHEK1 activates CDC25C through phosphorylation, relieving CDK1 inhibition and promoting the G2/M phase transition, thus accelerating proliferation." (PMID 41564103, 2026). "Berberine manifests anti-hepatocellular carcinoma activities primarily via coordinated targeting of AURKA and CDK1, essential cell cycle modulators." (PMID 41226349, 2025).
hepatocellular carcinoma (continued). "YOD1 regulates the stability of PML/RARα, CDK1, and ITCH, promoting malignant phenotypes in acute promyelocytic leukemia, triple-negative breast cancer, and hepatocellular carcinoma, respectively." (PMID 40274778, 2025). "Among them, CDK1, CHEK1, TYMS, KIF11, MMP12, TK1 and CA12 were differentially highly expressed in hepatocellular carcinoma tissues." (PMID 38842135, 2024). "The TCGA hepatocellular carcinoma cohort was used for internal and external validation and further screening to derive the three core genetic markers, including NR1I2, CDK1, and CHEK1." (PMID 38842135, 2024). "CDK1 and CCND1 are the key enzymatic complex required for mitosis, and normally activated to regulate the cell cycle of hepatocellular carcinoma cell adhesion." (PMID 35836300, 2022). "We also found that the expression of CDK1 and CCND1 was upregulated in HepG2 hepatoma cells following a 2.5 μM arecoline treatment." (PMID 35836300, 2022). "Our results provided a novel panel of AURKA, CDK1, TOP2A, CYP2C9, and CYP3A4 candidate genes for curcumin related chemotherapy of hepatocellular carcinoma." (PMID 35078445, 2022). "CDK1, also co-expressed with KPNA2, promotes G2/M cell cycle transition and has previously been reported in hepatocellular carcinomas." (PMID 35948941, 2022). "It has been documented that CDK1 links communications between the TME and tumor cells in hepatocellular carcinoma." (PMID 35681641, 2022). "AURKA, CDK1, CCNB1 and TOP2A were significantly upregulated and correlated with poor prognosis in hepatocellular carcinoma, AUC values of which were 95.7, 96.9, 98.1 and 96.1% respectively." (PMID 35078445, 2022). "In summary, CDK1, CCND1, RAF1, CDKN1B and BTRC were defined as top 5 hub target-genes, and the patients with hepatocellular cancer with high expression of CDK1 showed poor prognosis." (PMID 35836300, 2022). "Blocking CDK1/PDK1/β-Catenin signaling would inhibit proliferation and EMT of hepatocellular carcinoma cells." (PMID 35078445, 2022). "Costunolide, a eudesmanolide skeleton, induced mitotic arrest, but not progression to the G2 phase, by upregulating the expression of p-Cdk1 (Tyr 15) and cyclin B1 in HA22T/VGH hepatoma cells." (PMID 35056723, 2022). "Inhibition of the CDK1/PDK1/β-catenin signaling axis downregulates CSCs phenotype formation and enhances hepatocellular cancer sensitivity to sorafenib therapy." (PMID 34768921, 2021). "Overexpression of CDK1, CCNB1 and CDC20 in tumor tissues predicted poor survival of patients with hepatocellular carcinoma." (PMID 34253236, 2021). "In hepatoma cells, the target gene PLK1 of lncRNAP26302 was overexpressed, inhibiting the expression of Myt1 and reducing the inhibitory effect of Myt1 on CycA/CDK1." (PMID 30364632, 2018). "Two target genes of E2F4, CDK1 and TP73 were also involved in liver cancer development and proposed as prognostic marker of poor patient survival prognosis in hepatocellular carcinoma." (PMID 28347313, 2017). "We made several novel predictions, including that CDK1 and PTPN1 knockdown would be more effective in males with hepatocellular carcinoma, and SMAD3 and HSPA4 knockdown would be more effective in females with head and neck squamous cell carcinoma." (PMID 26755347, 2016). "Among the 14 intersecting genes, lasso regression was used to screen for genes with higher prognostic correlation with hepatocellular carcinoma, and a crossover test was performed to screen for three genes with higher prognostic correlation with patients—NR1I2, CDK1, and CHEK1." (PMID 38842135, 2024). "MCM7 inhibition led to a decrease in the esophagus and hepatocellular carcinomas viability, colony-forming ability, and migration capacity due to reducing phosphorylation of AKT1 and mTOR proteins with decreasing CDK1, CCNE1, and CCNE2 expression levels." (PMID 37529110, 2023).
hepatocellular carcinoma (continued). "The modes of action of drug-molecule interactions that may be effective against hepatocellular carcinoma core genes CCNA2, CCNB1, and CDK1 were investigated." (PMID 36479313, 2022). "When we merged these hub genes with differentially expressed genes in GSE14520 dataset and differentially expressed genes of hepatocellular carcinoma in GEPIA database, seven communal genes were found, they were AURKA, CDK1, CCNB1, TOP2A, CYP3A4, CYP2C9, and CYP2B6." (PMID 35078445, 2022). "Otherwise, accumulating studies have shown that curcumin and its analogs significantly downregulated the expression of CDK1 to induce cell cycle arrest in various human cancers, but not in hepatocellular carcinoma." (PMID 35078445, 2022). "The results showed that AC099850.3 could promote the migration and proliferation of hepatocellular carcinoma cells in vitro, and RT-PCR experiments found that AC099850.3 could promote the expression of the cell cycle molecules BUB1, CDK1, PLK1, and TTK." (PMID 34123835, 2021). "Adopting a series of bioinformatics analysis methods, the current study identified 763 DEGs and seven hub genes (CDC20, CDK1, MAD2L1, BUB1, BUB1B, CCNB1, and CCNA2) that may be involved in hepatocellular carcinoma tumorigenesis and progression." (PMID 33767726, 2021). "CDK1 and CCNB1 have been reported to promote the development of glioblastoma malignancies and are considered potential prognostic biomarkers or therapeutic targets for patients with hepatocellular carcinoma." (PMID 31870357, 2019). "The downregulation of CDK1 as a consequence of exposure to the HSP90 inhibitors has been reported in different studies, such as by ganetespib in mantle cell lymphoma, tanespimycin in colon cancer, or by 17DMAG, a semi-synthetic derivative of geldanamycin in hepatocellular carcinoma." (PMID 40282517, 2025). "Thus, our results indicated that curcumin might decrease the expression of AURKA, CDK1 and TOP2A to reverse chemoresistance in hepatocellular carcinoma treatment." (PMID 35078445, 2022). "Taken these together, our results suggested that the lower dose curcumin treatment might not induced sufficient downregulation of AURKA or CDK1 to inhibit proliferation of hepatocellular carcinoma cells." (PMID 35078445, 2022). "In summary, so far as we known, our results first showed that CDK1, TOP2A, CYP2C9, and CYP3A4 genes correlated to curcumin-related chemotherapy of hepatocellular carcinoma, more than just correlated to diagnosis and prognosis of hepatocellular carcinoma which had highlighted by the previous studies." (PMID 35078445, 2022). "It is suggested that the combined action of 6-shogaol and curcumin against hepatocellular carcinoma may be related to the inhibition of PI3/AKT and MAPK signalling pathways, upregulation of Bax and Caspase-3 proteins, and downregulation of Bcl-2, Cyclin-B, and CDK-1 proteins." (PMID 39224778, 2024). "The cell cycle-related molecules CDK1 and CCNB1 are the most connected hub genes, and these genes have been reported to be potential diagnostic or prognostic markers in a variety of tumours, such as glioblastoma malignancies, hepatocellular carcinoma and non-muscle invasive bladder cancer." (PMID 31870357, 2019).
ovarian carcinoma (90 papers, 2011 to 2026). A malignant neoplasm originating from the surface ovarian epithelium. "Dysregulation of CDK1 activity has been implicated in various malignancies, including ovarian cancer, contributing to uncontrolled cell proliferation and resistance to conventional therapies." (PMID 41009727, 2025). "In 147 patients with epithelial ovarian cancer, the overexpression of CDK1 was significantly associated with poor prognosis compared with a low expression group." (PMID 37569750, 2023). "To elucidate the underlying mechanism by which HADHA regulates ovarian cancer, we identified CDK1 as a target of HADHA." (PMID 37986001, 2023). "The TTK, NEK2, and CDK1 are over-expressed, demonstrating a high frequency of genetic alterations, and are associated with poor prognosis of ovarian cancer cohorts." (PMID 34072728, 2021). "And also, accumulated cytoplasmic Cdk1 is associated with 5-year overall survival in ovarian cancer patients." (PMID 27385216, 2016). "Furthermore, the HADHA has been implicated in fostering ovarian cancer progression through the up-regulation of CDK1 and is identified as a potential risk factor for malignant lymphoma." (PMID 38637116, 2024). "In addition, CDK1 is associated with poor prognosis in human pharyngeal squamous cell carcinoma, prostate cancer, ovarian cancer, oral squamous cell carcinoma, pancreatic ductal adenocarcinoma and other cancers." (PMID 33765954, 2021). "In conclusion, TTK, NEK2, and CDK1 are strongly associated with tumorigenesis, therapeutic resistance, and poor prognosis of ovarian carcinoma and thus serve as a novel biomarker for diagnosis as well as attractive therapeutic targets for the treatment of ovarian carcinoma." (PMID 34072728, 2021). "Thus, targeting the SL partner gene CDK1 in ovarian cancer patients carrying a KRAS mutation could be a good choice in anticancer drug research and development." (PMID 29855504, 2018). "In conclusion, our integrated approach identified CDK1 as a central regulatory hub in ovarian epithelial cancer and revealed Naringin as a promising dual-target inhibitor of both CDK1 and WEE1." (PMID 41009727, 2025). "Significant blockade of G2/M transition has been observed in ovarian cancer cells with inhibited CDK1, leading to reduced cellular proliferation and increased apoptosis." (PMID 41009727, 2025). "Analysis of GEPIA and Oncomine databases identified a robust correlation between WEE1 and CDK1 expression in ovarian cancer, indicating potential reciprocal regulation." (PMID 41009727, 2025). "Our results demonstrate that reducing WDR62 expression in ovarian cancer cells significantly decreases the levels of cell cycle-related proteins CDK1 and C-Myc in vitro." (PMID 40369663, 2025). "The extensive connectivity of CDK1 in this network reflects its integrative role in coordinating diverse signaling pathways and reinforces its potential as a global regulatory hub in ovarian cancer biology." (PMID 41009727, 2025). "CDK1 inhibitor RO-3306 has anti-tumor effects in ovarian cancer cells and mouse xenograft models implanted with ovarian cancer cells." (PMID 40290126, 2025).